INS (insulin)
Diseases named in the same sentence as INS in open-access papers (continued):
Sharing a sentence is not in itself a finding about the gene and the disease.
type 2 diabetes (continued). "This might reduce their ability to expand under conditions of increased insulin demand, favouring the development of type 2 diabetes." (PMID 26474776, 2016). "We sequentially excluded 31 224 people with type 1 diabetes (5.1%), 748 (0.1%) without a Townsend deprivation score, and 99 745 prescribed glitazones, gliptins, or insulin in the 12 months before the study entry date, leaving 469 688 patients with type 2 diabetes in the study cohort." (PMID 27413012, 2016). "Interestingly, miR-124a plays a role in beta cell development and insulin secretion, while miR-383 is differentially expressed in db/db mice and in mice fed a high-fat diet, two models of type 2 diabetes." (PMID 26474776, 2016). "Previous studies have demonstrated that insulin secretion may be suppressed by ghrelin, and pharmacological blockade of ghrelin maybe used to treat type 2 diabetes." (PMID 26918825, 2016). "The main characteristics of type 2 diabetes in humans were also detected in the model (neonatal streptozotocin induced diabetic rat) used in the present study, as for example mild fasting hyperglycemy, high insulin levels and some degree of insulin resistance." (PMID 27490892, 2016). "Among the patients with type 2 diabetes, only two were on insulin in addition to OHAs." (PMID 27904654, 2016). "Insulin therapy in type 2 diabetes may increase mortality and cancer incidence, but the impact of different types of basal insulins on these endpoints is unclear." (PMID 27031113, 2016). "There have been several papers about insulin dosing in type 2 diabetes (T2D)." (PMID 27457238, 2016). "Here we review data supporting the hypothesis that increasing energy and substrate turnover has beneficial effects on insulin sensitivity and should be considered a target for the prevention and treatment of type 2 diabetes." (PMID 27591854, 2016). "The progressive nature of type 2 diabetes despite the use of diet, physical activity and current therapies, such as metformin, sulfonylurea and insulin, may explain why therapeutic requirements tend to increase with time." (PMID 27669277, 2016). "Initiation and titration of human regular U-500 insulin (U-500R) with a dosing algorithm of either thrice daily (TID) or twice daily (BID) improved glycemic control with fewer injections in patients with type 2 diabetes treated with high-dose, high-volume U-100 insulin." (PMID 27716283, 2016). "While the FII is determined in healthy subjects, our previous studies suggest that the FII may be relevant to predicting exogenous prandial insulin doses in type 1 diabetes and reducing postprandial insulinaemia in type 2 diabetes." (PMID 27070641, 2016). "However, the reversing of ER stress and its associated improvement in the protein folding process resulted in increased insulin sensitivity and reverted type 2 diabetes in obese mice." (PMID 27517904, 2016). "Previous studies in PCOS, type 2 diabetes and/or obesity that prescribed aerobic, mixed training, and/or diet plus exercise have reported significant reductions in fasting insulin and fasting glucose and therefore this outcome requires further exploration in PCOS." (PMID 27175282, 2016). "Both the point estimate of the reported MACE frequency and estimated risk ratios showed that mealtime pramlintide as an adjunct to insulin conferred no increased risk of cardiovascular AEs in patients with type 2 diabetes using insulin." (PMID 28702246, 2016). "Metformin, an insulin-sensitizing drug, is a first line treatment for type 2 diabetes." (PMID 27513580, 2016). "Indeed, miR-223 regulates glucose metabolism and GLUT4 expression in neonatal rat cardiomyocytes, is up-regulated in insulin-resistant human hearts and down-regulated in plasma from patients with type 2 diabetes." (PMID 26962854, 2016). "Additionally, adult GK rats exhibit spontaneous type 2 diabetes with impaired glucose-induced insulin secretion, decreased β-cell mass, and hepatic glucose overproduction in the liver." (PMID 27069931, 2016).
type 2 diabetes (continued). "Type 2 diabetes is induced by impaired insulin sensitivity and secretion." (PMID 26978400, 2016). "In this respect, an insulin pump therapy using short-acting insulin analogues may be an even more interesting model for patients with type 2 diabetes: Glucose variability is further reduced compared to a MDI with short and long-acting insulin analogues." (PMID 26772807, 2016). "Therefore, early intensive insulin therapy is used as the ideal therapy to restore the β-cell function and to eliminate glucotoxicity in patients with newly diagnosed type 2 diabetes." (PMID 26697503, 2016). "A suggestion could be to develop additional subscales focusing on insulin-pump use, newer types of insulin, various types of glucose-lowering medications for type 2 diabetes and maybe also questions related to blood pressure and lipid-lowering actions." (PMID 27366112, 2016). "However, according to the national, evidence-based guidelines, generally only metformin is to be continued when add-on insulin treatment is initiated for patients with type 2 diabetes." (PMID 27031113, 2016). "Thus, during the development of the type 2 diabetes, increasing serum concentrations of insulin and leptin, decreasing plasma ghrelin, and declining ghrelin’s stimulation on hypothalamic ARC NPY neurons were observed from the control group to the DIO8W group." (PMID 27867820, 2016). "The results of our study showed that the serum amylase levels were positively associated with insulin secretion, as measured by AUCins/glu, and insulin sensitivity, as measured by ISIMatsuda, in type 2 diabetic patients, even after adjusting for anthropometric indices and metabolic risk factors." (PMID 27606813, 2016). "Their failure during type 2 diabetes mellitus may lead to reduced insulin secretion and impaired glucose homeostasis." (PMID 27452146, 2016). "The major constituents of astragalus are polysaccharoses, astragaloside, and isoflavones, have been shown to differentially lower high blood glucose and triglyceride levels, improve impaired glucose tolerance and increase insulin sensitivity in skeletal muscle in models of type 2 diabetes." (PMID 27422712, 2016). "Indeed, in GK rats, blood glucose levels after oral glucose loading were significantly lower in DSC108-pretreated rats than in vehicle-pretreated rats, indicating that DSC108 has an anti-hyperglycemic effect in type 2 diabetes by stimulating insulin secretion." (PMID 27764176, 2016). "Even in type 2 diabetes, the Matsuda index was correlated to clamp-derived insulin sensitivity." (PMID 26752053, 2016). "We have studied anxiety and depression as risk factors early in the course of the disease by including the large, relatively homogenous sample of insulin naïve people with Type 2 diabetes who were followed for a relatively long period with mortality as the endpoint." (PMID 27537359, 2016). "This is the first analysis of prospective and comprehensive patient-reported outcomes from a randomized, clinical trial of severely insulin-resistant patients with type 2 diabetes who were switched from high-dose U-100 insulin regimens to U-500R as insulin monotherapy." (PMID 27716283, 2016). "Chronically disrupted sleep may also lead to decreased insulin sensitivity, increased blood glucose levels and may thus lead to a higher prevalence of type 2 diabetes." (PMID 26918440, 2016). "First, levels of insulin and C-peptide immediately after ingestion of rice are much lower in type 2 diabetes compared with controls, while AUC−15–240 min-insulin in type 2 diabetes and AUC−15–240 min-C-peptide is comparable between type 2 diabetes and controls." (PMID 26704625, 2016). "Bavachin might have therapeutic potential for type 2 diabetes by activating insulin signaling pathways." (PMID 27070585, 2016). "When such insulin secretory defects are superimposed over an increased need for insulin as observed in old age, impaired glucose tolerance and type 2 diabetes may ensue." (PMID 26699651, 2016).
type 2 diabetes (continued). "This suggests that the genetic variation of rs1551305 in TPCN2 might be associated with insulin; however, the precise role of TPCN2 with regard to type 2 diabetes risk is still under investigation." (PMID 26918892, 2016). "The fact that PDGF-CC-induced WAT browning increases glucose tolerance and insulin sensitivity in HFD-induced obese animals suggests that PDGF-CC-induced WAT browning may be considered for treatment of type 2 diabetes in human patients." (PMID 27492130, 2016). "The acute increase in circulating insulin observed in the present study may therefore be of benefit to individuals with type 2 diabetes; however, the chronic effects in healthy, insulin sensitive individuals is less clear." (PMID 26927166, 2016). "Liraglutide might be useful for treating insulin allergy and anti-insulin antibodies in patients with type 2 diabetes." (PMID 27456688, 2016). "Similar to Japanese, East-Asian patients with type 2 diabetes exhibited stronger association of insulin secretory capacity with glucose intolerance without morbid obesity." (PMID 26788515, 2016). "However, as the decrease in insulin secretion itself takes longer to induce type 2 diabetes, a high-fat diet was fed to exacerbate glucose homeostasis and require more insulin secretion by increasing insulin resistance." (PMID 26978400, 2016). "Ng and colleagues found that, for a Canadian cohort of patients with type 2 diabetes, those taking insulin had a significantly higher likelihood of a hospitalization (OR = 1.7, 95 % CI: 1.4–2.0), controlling for numerous demographic, socioeconomic, and health-status characteristics." (PMID 26786291, 2016). "Also, anxious people with insulin-naïve Type 2 diabetes more often fear hypoglycemia, insulin injections or blood glucose self-testing, a fear which has shown to be a barrier to insulin treatment in previous studies." (PMID 27537359, 2016). "No studies have established whether the use of metformin with insulin is beneficial and the growing incidence of type 2 diabetes in pregnant mothers makes this an increasingly relevant and important question." (PMID 27435163, 2016). "Furthermore, leptin is angiogenic during tumorigenesis, and insulin is involved in type-2 diabetes-mediated mammary tumor progression in mice." (PMID 27582541, 2016). "Congruent with its effect on insulin secretion, high levels of miR-375 correlate with the incidence of diabetes and miR-375 has been suggested as a biomarker for not only cancer but Type 2 diabetes as well." (PMID 27434126, 2016). "Under insulin-resistant conditions, impaired insulin action promotes hepatic glucose production and decreases glucose uptake in peripheral tissues such as muscle and fat, resulting in hyperglycemia (high blood glucose), i.e., type II diabetes." (PMID 28025491, 2016). "Our data shows that a large proportion of non-obese Iraqi males and females are insulin resistant which implies a high risk for type 2 diabetes." (PMID 27938404, 2016). "Cholesterol and insulin (both of which are elevated in Type 2 diabetes) increase HIF-1alpha." (PMID 27434126, 2016). "Based on data obtained from animal studies and adults with type 2 diabetes it seems that the lower concentrations of gastrointestinal peptides and adipocytokines are responsible for lower insulin sensitivity and glucose metabolism in comparison with the general population." (PMID 26904686, 2016). "Active components of S. miltiorrhiza depside salt may play a more important role in endocrine system, such as type II diabetes mellitus, insulin signaling pathway, and adipocytokine signaling pathway." (PMID 27069488, 2016). "Type 2 diabetes (formerly called noninsulin-dependent or adult-onset diabetes) is caused by ineffective use of insulin in the body." (PMID 27769953, 2016). "Cigarette smoking is an independent and modifiable risk factor for type 2 diabetes; however, the evidence for insulin sensitivity and metabolic syndrome is not sufficient to conclude." (PMID 26845035, 2016).
type 2 diabetes (continued). "MI may precipitate hyperglycemia and DKA via an increase in counterregulatory hormones, such as epinephrine, both in type 1 and type 2 diabetes—mainly the subpopulation of type 2 diabetics with decreased insulin production suffering severe stress." (PMID 27975067, 2016). "In addition, oral administration of DSC108-Na improved glucose tolerance in the Goto-Kakizaki (GK) rat, which is a model of type 2 diabetes with impaired insulin secretion." (PMID 27764176, 2016). "Hypoglycemia is a common side effect of insulin therapy in type 1 and type 2 diabetes." (PMID 27994961, 2016). "In a similar way, reports indicated that the insulin-mimetic action of vanadium in type 2 diabetic patients could improve carbohydrate metabolism and reverse hyper-glycemia." (PMID 26459400, 2016). "In 1991, almost all patients using insulin for type 2 diabetes did so as monotherapy." (PMID 27152598, 2016). "Thus, the tight regulation of insulin resistance and β-cell function play important roles in the prevention of type 2 diabetes as well as in delaying its progression." (PMID 26884795, 2016). "Another possible hypothesis is that obesity could have different effects on insulin sensitivity in type 1 and type 2 diabetes." (PMID 27011769, 2016). "The results provide evidence that APE may improve hyperglycaemia in type 2 diabetes because skeletal muscle is the major tissue responsible for glucose uptake in response to insulin." (PMID 27141227, 2016). "To address this paradox, we proposed the hypothesis that Irs1-mediated insulin signalling is enhanced, whereas Irs2-mediated insulin signalling is impaired in the liver in type 2 diabetes and obesity." (PMID 27708333, 2016). "In one mouse model of Type 2 Diabetes (T2DM) pre-treatment with oleic acid reversed the inhibitory effects of TNFα on insulin production, while in vivo, oleic acid-treated cells resulted in elevated translocation of the PPAR-activated receptor transcription factor to the nucleus." (PMID 27531998, 2016). "Insulin secretagogues such as sulfonylureas and glinides have been widely used to treat patients with type 2 diabetes, but can increase the risk of hypoglycemia since they trigger insulin release from pancreatic islets independent of ambient glucose levels." (PMID 27104960, 2016). "In conclusion, habitual resistance exercise in type 2 diabetic rats increased muscular sex steroid hormone levels and concomitantly induced muscle hypertrophy and improved hyperglycemia and insulin sensitivity index by activating GLUT-4–regulated signaling in skeletal muscle." (PMID 27832095, 2016). "Previous reports indicate that higher protein expression of GSK-3 (often elevated in patients with type 2 diabetes) is related to lower insulin action in skeletal muscle, whereas GSK-3 in adipose tissue is less likely to play a role in whole body glucose disposal." (PMID 27754361, 2016). "A similar mechanism (uncovered by a validated numerical study) was speculated to be present in type 2 diabetics who were receiving continuous enteral feedings and SQ insulin therapies for their hyperglycemia." (PMID 26819233, 2016). "However, the HOMA-IR also present relatively low value when the insulin secretion decreases in people with advanced type 2 diabetes, because the HOMA-IR is acquired by multiplying the fasting glucose and insulin levels." (PMID 26752053, 2016). "Elevated depressive symptoms were associated with excess mortality risk in people with Type 2 diabetes not using insulin." (PMID 27537359, 2016). "Such heterogeneity may be relevant for type 2 diabetes pathogenesis, since specific insults might target single cells or defined islet regions to induce insulin secretory failure." (PMID 27452146, 2016).
type 2 diabetes (continued). "Adipokines are involved in regulating glucose metabolism, insulin signaling pathway, lipid and lipoproteins metabolism and inflammation, which in this way interact with the pathogenesis of type 2 diabetes mellitus (T2DM), metabolic syndrome and atherosclerotic cardiovascular disease." (PMID 28033351, 2016). "This however was not the case, indicating that the hyperglycemia in the GK+/−ApoE−/− knockout mice is predominantly due to inadequate compensatory insulin secretory response, possibly as a result of impaired β-cell function, an important determinant of type 2 diabetes." (PMID 27774459, 2016). "In addition, different evidence suggests that metformin improves systemic insulin sensitivity through the regulation of SeP production, suggesting a novel potential therapeutic approach to treating type 2 diabetes." (PMID 27973438, 2016). "The best-performing alternative was the combination of an age cut-off of 39 years and time to insulin of 12 months; this improved the correct classification of those with type 2 diabetes to 94%, but reduced to 78.3% those correctly classified with type 1 diabetes." (PMID 27080317, 2016). "Therefore, in this study the effects of i.c.v. injection of a GalR1 agonist, M617 on insulin sensitivity, and insulin signaling in the adipose tissue of type 2 diabetic rats were evaluated." (PMID 27127795, 2016). "Besides, in male patients with type 2 diabetes, the insulin sensitivity index increased following intake of 40 g alcohol (40% v/v)." (PMID 27231920, 2016). "Moreover, metformin is one of the most extensively used anti-diabetic medications by enhancing the insulin sensitivity in patients with type 2 diabetes." (PMID 26885898, 2016). "Insulin secretagogues are used for treatment of type 2 diabetes." (PMID 27764176, 2016). "Additionally, several studies have attributed to ascorbate supplementation an antidiabetic effect by improving whole body insulin sensitivity and glucose control in people with type 2 diabetes." (PMID 27834920, 2016). "Because type II diabetes is characterized by impaired insulin sensitivity, caffeine might play an important role in the protective effect of coffee against type II diabetes." (PMID 28031026, 2016). "It is possible that the dual effects of CE on both the storage and utilization of fat would be beneficial for obesity related to type II diabetes by increasing insulin sensitivity through enhanced lipid storage capacity and by utilizing stored fat to avoid excess fat accumulation." (PMID 28231178, 2016). "We propose that this regulation participates to the deleterious effects of GCs on beta cells and may explain the insulin secretion defect observed in situations of excess GCs concentrations and more generally in type 2 diabetes." (PMID 26901633, 2016). "Type 1 diabetes (juvenile diabetes, in which no insulin is made) is more likely to develop vision loss than type 2 diabetes (adult onset diabetes with insufficient insulin synthesis)." (PMID 26881246, 2016). "Type 2 diabetes arises from the body’s inability to respond to insulin produced by the pancreas." (PMID 27905277, 2016). "Insulin increases cell growth, thus it has been suggested that cardiac hypertrophy in type 2 diabetes may result from hyperinsulinemia." (PMID 27999359, 2016). "The high-fat diet- (HFD-) fed C57BL/6J mouse could induce early type 2 diabetes and markedly increased adipose weights and produced resistance to insulin and increases in blood glucose, total cholesterol (TC), and TG levels." (PMID 27242912, 2016). "Depending on the severity of the disease, physical activity and a dietary plan may be successful in the management or prevention of type 2 diabetes, but insulin and medications may also be required." (PMID 27775605, 2016).